TAS2R15P (taste 2 receptor member 15, pseudogene)
Synonyms: T2R15; PS8; TAS2R15
Gene: Unprocessed pseudogene on chromosome 12 (10,964,425 to 10,965,352, reverse strand). Ensembl gene ENSG00000212125.
Diseases named in the same sentence as TAS2R15P in open-access papers:
TAS2R15P is named in the same sentence as 2 diseases in open-access papers, as found by Europe PMC text mining. Sharing a sentence is not in itself a finding about the gene and the disease.
TAS2R15P shares sentences with these, for which no sentence is quoted: infection (1 paper); Lyme disease (1).